KDELR3 (KDEL endoplasmic reticulum protein retention receptor 3)
Description:
Receptor for the C-terminal sequence motif K-D-E-L that is present on endoplasmic reticulum resident proteins and that mediates their recycling from the Golgi back to the endoplasmic reticulum.
Synonyms: ERD23; ERD2L3
Tractability: Antibody: UniProt predicts a signal peptide or a membrane-spanning region.
Gene: Protein-coding gene on chromosome 22 (38,468,043 to 38,483,447, forward strand). Ensembl gene ENSG00000100196.
Subcellular location: Endoplasmic reticulum membrane; Golgi apparatus membrane; Cytoplasmic vesicle, COPI-coated vesicle membrane
Subcellular location (Human Protein Atlas): Endoplasmic reticulum
Pathways (Reactome):
Vesicle-mediated transport: COPI-dependent Golgi-to-ER retrograde traffic; COPI-mediated anterograde transport
Cellular responses to stimuli: XBP1(S) activates chaperone genes
Gene Ontology:
Molecular function: ER retention sequence binding
Biological process: retrograde vesicle-mediated transport, Golgi to endoplasmic reticulum; protein retention in ER lumen
Cellular component: COPI-coated vesicle membrane; endoplasmic reticulum; endoplasmic reticulum membrane; Golgi membrane; transport vesicle; membrane
Genetic constraint (gnomAD): Loss-of-function variants: 20 observed, 20.84 expected, observed/expected ratio (o/e) 0.96, 90% interval 0.67 to 1.39. The upper end of that interval is the gene's LOEUF score, 1.39, which puts it in group 5 of 6, group 1 being the genes least tolerant of losing a copy. Missense variants: 269 observed, 244.63 expected, observed/expected ratio (o/e) 1.1, 90% interval 1 to 1.22. Synonymous variants: 111 observed, 99.47 expected, observed/expected ratio (o/e) 1.12, 90% interval 0.96 to 1.31.
Homologues: Orthologues: chimpanzee KDELR3 (99% identical), macaque KDELR3 (99% identical), guinea pig KDELR3 (97% identical), pig KDELR3 (95% identical), dog KDELR3 (93% identical), mouse Kdelr3 (93% identical), rabbit KDELR3 (93% identical), tropical clawed frog kdelr3 (85% identical), rat Kdelr3 (81% identical), zebrafish kdelr3 (76% identical), Drosophila melanogaster KdelR (64% identical), Caenorhabditis elegans erd-2.2 (61% identical), and 2 more. Paralogues in human: KDELR2 (74% identical), KDELR1 (71% identical).
Diseases named in the same sentence as KDELR3 in open-access papers:
KDELR3 is named in the same sentence as 22 diseases in open-access papers, as found by Europe PMC text mining. Sharing a sentence is not in itself a finding about the gene and the disease. The quoted sentences say what the papers report.
melanoma (10 papers, 2020 to 2025). A malignant, usually aggressive tumor composed of atypical, neoplastic melanocytes. "PCOLCE was reported to be an important factor in the transition from telogen to anagen, and the expression of KDELR3 is associated with the development of melanocytes and the progression of melanoma." (PMID 35052373, 2021). "It was reported that the loss of KDELR3 in the genetically engineered mouse would lead to the metastasis depression of melanoma cells by interacting with KAI1, which was a metastasis suppressor." (PMID 34339395, 2021). "Kaplan-Meier plots of 2 survival-related UPRRGs manifested that high expression of TARS and KDELR3 was associated poor survival in melanoma." (PMID 33136551, 2020). "In particular, KDELR3 is upregulated in malignant melanoma, is localized at both the cis- and trans-Golgi compartments of metastatic melanoma cells and plays a key role in the metastatic process." (PMID 40767982, 2025). "KDELR3 knocked-down melanoma cell lines in the experimental tail vein metastasis assay showed reduced metastatic potential, with no appreciable difference in subcutaneous in-vivo tumour growth." (PMID 40767982, 2025). "According to the findings of the study carried out by Marie and colleagues, the inhibition of KDELR3 led to a reduction in the amount of melanoma cells that colonized the lungs during experimental metastasis assays." (PMID 36046379, 2022). "Metastatic melanoma patients with KDELR3 copy number amplifications demonstrated reduced survival relative to patients without such alterations." (PMID 31949145, 2020). "To uncover the role of KDELR3 in melanoma metastasis, we asked which pathways were co-regulated with KDELR3 expression." (PMID 31949145, 2020). "Analysis of human patient datasets and tumor histology microarrays confirmed an upregulation of KDELR3 expression in malignant melanoma vs. benign nevi." (PMID 31949145, 2020). "We anticipate that further exploration of KDELR3 and other now-uncovered embryonic genes/pathways will facilitate the development of more effective treatment strategies for patients with advanced melanoma, and perhaps other tumor types." (PMID 31949145, 2020). "Here, the authors generate a melanoblast-specific transcriptome using a genetically engineered mouse model and identify KDELR3 as a pro-metastasis gene in melanoma." (PMID 31949145, 2020). "To further understand the role of KDELR3 in metastasis, we queried if KDELR3 knockdown would increase expression of known metastasis suppressors in melanoma." (PMID 31949145, 2020). "We next assessed melanoma patient survival using KDELR3 expression as a prognostic marker (GEO25,27)." (PMID 31949145, 2020). "We used human and mouse melanoma cells to demonstrate that siRNA and short-hairpin RNA (shRNA) knockdown of KDELR3 significantly reduced, and KDELR3 overexpression enhanced, anchorage-independent growth, which cannot be attributed to a change in proliferation." (PMID 31949145, 2020). "KDELR3 was therefore validated as a mediator of anchorage-independent growth in melanoma cells, a process required for metastasis." (PMID 31949145, 2020). "To test this, we asked if KDELR3 knockdown sensitizes metastatic melanoma cells to ER stress-induced death." (PMID 31949145, 2020). "We demonstrate that the embryonic melanoblast gene, KDELR3, is a metastasis enhancer in both mouse and human melanoma cells, whereas KDELR1 suppresses metastasis, despite having extensive homology and similar retrograde-trafficking functions." (PMID 31949145, 2020). "We observed in four independent mouse models of melanoma (N = 6–13 mice per model) that Perk (Eif2ak3) transcription was negatively correlated with Kdelr3 transcription, whereas Gadd34 (Ppp1r15a) transcription was positively correlated." (PMID 31949145, 2020). "We showed that KDELR3 is localized to both the cis- and trans-Golgi compartments in metastatic melanoma cells and validated expression of KDELR3 in mouse melanoblasts." (PMID 31949145, 2020).
melanoma (continued). "Virtually all melanoma cell lines in the NCI60 were characterized by elevated KDELR3 expression, but reduced or unchanged expression of KDELR1 and KDELR2, respectively." (PMID 31949145, 2020). "KDELR1 and KDELR3 play an oppositive role during melanoma progression." (PMID 40767982, 2025). "KDELR3-knockdown melanocytes have an enhanced sensitivity to ER stress, suggesting an important role of this receptor as a promoter of metastatic cell survival in both mouse and human melanoma cells." (PMID 40767982, 2025). "Genetic deletion of KDELR3 was found to inhibit the lung metastasis of melanoma cells." (PMID 34930465, 2021). "Moreover, within the KDELR family only KDELR3 demonstrated a melanoblast-specific expression pattern and showed consistent upregulation in melanoma cell lines." (PMID 31949145, 2020). "We sought to functionally validate a role of KDELR3 in melanoma progression." (PMID 31949145, 2020). "However, no appreciable difference in cell cycle or subcutaneous in vivo tumor growth was observed, suggesting that the KDELR3-mediated metastatic phenotype cannot be attributed to a change in proliferation, and that KDELR3 is a genuine melanoma metastasis progression gene." (PMID 31949145, 2020). "KDELR3, a member of the KDEL receptor family, has been reported as a genuine melanoma metastasis progression gene." (PMID 36081847, 2022). "To address this, we screened protein expression of five melanoma metastasis suppressors (BRMS1, gelsolin, GAS1, NME1/NM23-H1, and KAI1) following KDELR3 knockdown." (PMID 31949145, 2020). "We show that KDELR3 expression is critical for adaptation of melanoma cells to ER stress and provides evidence that PERK–EIF2α expression and activation are regulated by changes in KDELR3 expression levels." (PMID 31949145, 2020). "These genes contained KDELR3, EIF4EBP1, TARS, MTHFD2, SHC1 which all highly expressed in melanoma compared to normal skin in The Human Protein Atlas." (PMID 33136551, 2020). "In this research, we further distinguished 5 differentially expressed UPRRGs (KDELR3, EIF4EBP1, TARS, MTHFD2 and SHC1), which also highly expressed in melanoma at the protein level." (PMID 33136551, 2020). "Our data demonstrating reduced BiP protein in stable KDELR3-knockdown cells suggest that BiP is a genuine substrate for KDELR3 retrograde trafficking, and that without KDELR3 expression melanoma cells are unable to maintain normal BiP levels." (PMID 31949145, 2020). "Notably, in contrast to KDELR3 knockdown, which predictably diminished metastasis, KDELR1 knockdown actually increased metastasis, suggesting that KDELR1 contributes in a very different way to melanoma etiology and can function as a metastasis suppressor." (PMID 31949145, 2020).
hepatocellular carcinoma (4 papers, 2022 to 2025). A malignant tumor that arises from hepatocytes. "In addition, several studies have found that KDELR3 is significantly aberrantly expressed in a variety of malignancies, including prostate adenocarcinoma and hepatocellular carcinoma." (PMID 37138862, 2023). "Moreover, elevated KDELR3 expression was recently reported in patients with hepatocellular carcinoma and associated with other genes as markers for a negative disease prognosis." (PMID 36614300, 2023). "Among the eight mRNAs in the model, the up-expressions of TKTL1, KDELR3, PFKP, SLC2A1, and PGF in hepatocellular carcinoma were confirmed in previous experimental studies, while the over-expression of SAP30 in HCC was reported in an earlier computational study." (PMID 36362375, 2022). "We obtained a prognostic signature including eight hypoxia genes (ENO2, KDELR3, PFKP, SLC2A1, PGF, PPFIA4, SAP30, and TKTL1) and further established a hypoxia-related prognostic ceRNA network including 17 lncRNAs, six miRNAs, and seven mRNAs for hepatocellular carcinoma." (PMID 36362375, 2022).
uveal melanoma (3 papers, 2020 to 2022). A melanoma derived from melanocytes of the uveal tract. "KDELR3 is considered to be one of genes that formed 11-gene-based prognostic signature of uveal melanoma." (PMID 34035809, 2021).
prostate adenocarcinoma (2 papers, 2021 to 2023). "Another study identified five glycolysis-related mRNAs (GYS2, STMN1, PPFIA4, KDELR3, and ABCB6) which were associated with patients experience biochemical recurrence (BCR) after radical prostatectomy (RP) in patients with prostate adenocarcinoma." (PMID 34489401, 2021).
Alzheimer disease (1 paper, 2022). A progressive, neurodegenerative disease characterized by loss of function and death of nerve cells in several areas of the brain leading to loss of cognitive function such as memory and language. "Our findings suggested that KDELR3 may play an important role in the progression of neurodegeneration-multiple diseases, amyotrophic lateral sclerosis, Alzheimer's disease, Parkinson's disease, Huntington's disease, prion disease, and thermogenesis." (PMID 36046379, 2022).
arteriosclerosis (1 paper, 2021). A vascular disorder characterized by thickening and hardening of the walls of the arteries. "Reports have shown previously that KDELR3 expression in arteriosclerosis macrophages could be obviously differ from that in non-arteriosclerosis tissues, and the higher expression level in non-arteriosclerosis tissues, which can be used as a potential prognostic factor." (PMID 33912215, 2021).
diabetes (1 paper, 2023). "This is another evidence that links Kdelr3 to the susceptibility of T2D diabetes, given the reports of overloaded misfolded proteins as hallmark for beta cell dysfunction and apoptosis in the disease." (PMID 36614300, 2023). "However, the exact mechanism underlying the association of Kdelr3 to diabetes risk and to beta cell stability remains to be clarified in future studies." (PMID 36614300, 2023).
dysferlinopathy (1 paper, 2023). "Comparative analysis between PM and dysferlinopathy revealed that the DEGs upregulated in PM were most abundant in the protein localization to organelle pathway and helped identify four genes (KDELR3, C0PB2, TMED7, and RAB1A) that were related to ER to Golgi vesicle–mediated transport." (PMID 38125829, 2023).
insulinoma (1 paper, 2023). "In a previous study, Kdelr3 upregulation was observed upon treatment of the insulinoma INS1-E cells with the ER stress-inducing compound Thapsigargin." (PMID 36614300, 2023). "RNA interference-mediated knockdown (KD) of Kdelr3 in the insulinoma cell line MIN6 led to a significant reduction (70%) of Kdelr3 gene expression compared to cells transfected with the non-target control siRNA oligonucleotides (NTC)." (PMID 36614300, 2023). "Thus, we further investigated the impact of a Kdelr3 depletion in the insulinoma beta cell line MIN6." (PMID 36614300, 2023).
metastatic melanoma (1 paper, 2020). A melanoma that has spread from its primary site to another anatomic site. "High KDELR3-expressing late-stage metastatic melanomas showed statistically significant association with poor patient outcome, whereas KDELR3 expression levels in early-stage primary tumor samples did not." (PMID 31949145, 2020). "Taken together, these data strongly support a role for KDELR3 in the advancement of late-stage metastatic melanoma and implicate KDELR3 as a bona fide MetDev gene." (PMID 31949145, 2020). "We observed that siRNA-mediated knockdown of KDELR3 expression resulted in a ~5-fold increase in metastatic melanoma cell death over controls (8.3%, siKDELR3; 1.6%, siControl)." (PMID 31949145, 2020). "We found that, contrary to metastatic melanoma, loss of KDELR3 in these cells is not critical for cell viability." (PMID 31949145, 2020). "This biology may be informative for developing therapeutics for KDELR3-high metastatic melanoma patients." (PMID 31949145, 2020). "To further validate the role of KDELR3 on KAI1 protein regulation, we exogenously expressed KAI1 protein in 1205Lu metastatic melanoma cells (in which endogenous KAI1 expression is relatively low) and co-expressed KDELR3-001, KDELR3-002, or a vector control." (PMID 31949145, 2020). "If our hypothesis is correct, we expect KDELR3 to be critical to metastatic melanoma viability, but not to normal melanocytes." (PMID 31949145, 2020).
myopia (1 paper, 2024). "There were no cases had rare PTV in KDELR3 or P/LP variants in known myopia genes." (PMID 39112444, 2024).
skin cutaneous melanoma (1 paper, 2020). "KDELR3 has neither been previously associated with cutaneous melanoma metastasis nor investigated in depth in the literature." (PMID 31949145, 2020).
cancer (7 papers, 2020 to 2024). A tumor composed of atypical neoplastic, often pleomorphic cells that invade other tissues. "This study, for the first time, demonstrated the cancer‐promoting properties of KDELR3 in PAAD, providing novel insights into the mechanisms underlying PAAD progression." (PMID 38303549, 2024). "In the present investigation, we began by conducting pan-cancer assays, and we discovered that the level of KDELR3 was noticeably elevated in the majority of different kinds of cancers." (PMID 36046379, 2022). "Notably, key players in glycolysis such as ALDOB and KDELR3 genes are increased in LYZ+ cancer cells." (PMID 38659853, 2024). "This suggested that KDELR3 exerts oncogenic effects in various cancers." (PMID 38303549, 2024). "Limited studies have examined the functions of KDELR3 in cancer." (PMID 38303549, 2024). "Thus, KDELR3 is a critical regulator of ERS and UPR and is associated with the pathogenesis of various human diseases, such as cancers." (PMID 38303549, 2024). "The results of UALCAN database analysis showed that the mRNA expression levels of CALR, CREB3L3, FBOX6, and KDELR3 were increased in cancer tissues compared with normal tissues, while the mRNA expression levels of CRYAB, DNAJB4, and HSPB6 were decreased in BLCA." (PMID 34930465, 2021). "KDELR3 and YWHAZ possessed cancer‐promoting capacities, showing promise as a novel treatment target." (PMID 38303549, 2024). "Relative PAM, STC1, and HDAC4 expression were down-regulated, whereas CASP6, CHST6, SLC16A3, TPI1, KDELR3, VCAN, and CLDN9 were highly expressed in carcinoma tissues compared to the para-carcinoma tissues." (PMID 33424916, 2020). "We explored the relationship of KDELR3 expression and immune infiltration level based on CIBERSORT in order to identify whether KDELR3 expression was connected with the immune infiltration level in a variety of malignancies." (PMID 36046379, 2022). "In order to determine whether or not KDELR3 expression was correlated with cancer, we analyzed its levels in a variety of tumors as well as the normal tissues." (PMID 36046379, 2022).
tumor (6 papers, 2020 to 2025). "Our research contributed to a better understanding of the potential function of KDELR3 mRNA in tumor immunology as well as its relevance as a prognostic indicator." (PMID 36046379, 2022). "KDELR3, which was up-regulated in tumor samples and cell lines compared with that in adjacent normal tissues and normal cell lines, served as a predictor for poor prognosis of BCa." (PMID 34339395, 2021). "Silencing KDELR3 suppressed tumour growth in a xenograft model." (PMID 38303549, 2024). "KDELR3 knockdown markedly suppressed xenograft tumour growth." (PMID 38303549, 2024). "Western blot test manifested that the protein expressions of KDELR3 in xenograft tumours from the KDELR3 deletion group (sh‐KDELR3, S1‐S6) were significantly lower than that in the negative control group (sh‐vector, C1‐C6), which ensured the accuracy of the experiments." (PMID 38303549, 2024). "The BCL2L1, CAV1, KDELR3 and YWHAZ expression levels were upregulated in the tumour tissues and downregulated in the healthy pancreatic tissues." (PMID 38303549, 2024). "qRT‐PCR analyses revealed that the KDELR3 and YWHAZ in tumour samples were significantly higher than those in non‐cancerous samples." (PMID 38303549, 2024). "KDELR3 was mainly expressed in tumor cells, IDH2 was mainly expressed in endothelial cells, S100A6 was mainly expressed in photoreceptor cells, ITPA was mainly expressed in endothelial cells and tumor cells, PARP8 was mainly expressed in T cells, and APRC1B was mainly expressed in endothelial cells." (PMID 35242144, 2022).
KDELR3 also shares sentences with these, for which no sentence is quoted: amyotrophic lateral sclerosis (1 paper); bladder cancer (1); Cirrhosis (1); gastric cancer (1); Huntington disease (1); Parkinson disease (1); prion disease (1); Type 2 Diabetes (1).